INS (insulin)
Diseases named in the same sentence as INS in open-access papers (continued):
Sharing a sentence is not in itself a finding about the gene and the disease.
diabetes (continued). "In Norway, general practice provides care to the vast majority of people with T2D, and initiating insulin is often recognized as the most challenging step in the diabetes treatment cascade." (PMID 38116986, 2024). "It is also known that women are more sensitive to insulin compared to men, but this metabolic advantage gradually disappears after menopause or when IR progresses to hyperglycemia and diabetes." (PMID 39339706, 2024). "Regarding the link between IPMN and diabetes, it was found that patients with diabetes, especially those using insulin, have a higher incidence of BD-IPMN." (PMID 39202722, 2024). "Diabetes, insulin, and Rb1 groups significantly lowered body mass and serum insulin levels (P < 0.01) from control, and the insulin group increased body mass and serum insulin levels (P < 0.05)." (PMID 38961333, 2024). "Here we report the induction of islet autoimmunity to INS-DRiP and diabetes after ICI treatment and successful tumor remission." (PMID 38596681, 2024). "Considering the metabolic efficacy of tirzepatide, it appeared better than insulin in diabetes control." (PMID 39684653, 2024). "A closed loop artificial pancreas system, both in bihormonal (insulin+glucagon) and insulin-only configuration was compared with usual diabetes care in 3 adult patients." (PMID 38966218, 2024). "In our analysis of patients with type 2 diabetes, we observed a higher prevalence of insulin use in individuals with EOD diabetes (22.5%) compared to those with LOD diabetes (14.3%)." (PMID 37932230, 2024). "Patients with uncontrolled diabetes should be seen on a more regular basis (weekly or biweekly), especially those treated with insulin, in order to ensure that they understand insulin titration and that they avoid hypoglycaemia." (PMID 39063405, 2024). "The newest CGM devices continue to be smaller and more accurate, and integration with automated insulin delivery systems has further revolutionized the management of diabetes, leading to successful improvements in care and quality of life." (PMID 39306610, 2024). "Wang and Bao demonstrated that houttuynin can significantly alleviate diabetes symptoms by increasing adiponectin levels, which is a crucial factor for insulin sensitivity, and reducing connective tissue growth factors." (PMID 39334723, 2024). "It was investigated that the synthesis of apelin-12 in adipocytes is triggered by insulin, and its serum level is found to be increased in diabetes mellitus, hyperinsulinemia, and insulin resistance." (PMID 37930396, 2024). "Historical non-CF controls (N = 57) from the U.S. National Health and Nutrition Examination Survey (NHANES) dataset were frequency matched to participants with CF on age, sex, diabetes status, and insulin use." (PMID 38917148, 2024). "During tele-follow-up, the majority of patients on insulin therapy (n = 113; 78.5%) was provided with individualized guidance regarding dose adjustment by diabetes educators." (PMID 38469168, 2024). "Akkermansia muciniphila has been extensively studied in the treatment of metabolic disorders, which can improve insulin resistance and intestinal permeability, increase the energy consumption of obese mice after pasteurization, and thus alleviate diabetes." (PMID 39272484, 2024). "1.Apply insulin treatment.2.Oral administration of mosapride citrate tablets.3.Implement diet guidance according to diabetes nursing routine, and supervise their diet implementation." (PMID 38957444, 2024). "The amount and type of food consumed impacts the glycemic response and insulin needs of people with type 1 diabetes mellitus (T1DM)." (PMID 38638557, 2024). "Newly developed underweight group revealed more severe form of diabetes mellitus: longer duration (five years or longer), multiple oral hypoglycemic agents (≥ 3), insulin use, and higher fasting glucose." (PMID 38281993, 2024).
diabetes (continued). "Continuous glucose monitoring (CGM) systems and advanced insulin delivery methods, such as insulin pumps and hybrid closed-loop systems, are changing the landscape of diabetes care." (PMID 38337523, 2024). "Diabetes mellitus is a serious chronic disease characterized by elevated blood glucose concentrations related to the effects of abnormal β-cell biology on insulin action." (PMID 40302944, 2024). "Although H2O2 regulates cell growth, in type-1 diabetes mellitus the excess of intracellular ROS accumulation in β-cells leads to the failure of insulin secretion." (PMID 39125952, 2024). "Carbohydrate counting stands out as a key aspect of diabetes-specific nutrition education for individuals with T1D on multiple daily injections (MDIs) insulin therapy, as recommended by international guidelines." (PMID 39519579, 2024). "Transdifferentiation of different cell types into insulin-secreting cells is another attractive possibility for developing approaches to diabetes therapy." (PMID 39045459, 2024). "Plasma ceramide (14:0) is regarded as the strongest predictor of insulin resistance in obesity and diabetes because its decreased level is negatively correlated with increased insulin sensitivity." (PMID 39519451, 2024). "The insulin sensitizer metformin is a biguanide widely prescribed for the treatment of type 2 diabetes mellitus." (PMID 38594745, 2024). "Attaining the right balance becomes particularly essential for effective weight management, a key facet in diabetes care, as excess weight can heighten insulin resistance." (PMID 38421977, 2024). "Cui and colleagues have combined MEP with a micropump for insulin administration to construct a closed-loop system for diabetes management." (PMID 39434840, 2024). "Daily insulin requirements were significantly higher in women with pre-existing diabetes than in those with GDM (0.52 ± 0.35 vs 0.24 ± 0.12 units/kg, respectively, P < 0.001)." (PMID 40071056, 2024). "Omnipod is a tubeless, continuous insulin delivery device with two parts; a waterproof (IP28) wearable insulin patch pump (Pod) and a hand-held personal diabetes manager (PDM)." (PMID 37098714, 2024). "Particularly, in recent years, there has been significant interest in developing insulin delivery systems for the treatment of diabetes." (PMID 39065795, 2024). "Sesamin, the main bioactive compound in sesame seeds, can significantly ameliorate diabetes by enhancing insulin sensitivity, reducing inflammation, boosting antioxidant defenses, and regulating lipid metabolism." (PMID 39519546, 2024). "In diabetes, insulin signaling in the liver, skeletal muscle, and adipocytes is impaired, resulting in abnormal glucose metabolism." (PMID 39513056, 2024). "STZ, derived from Streptomyces bacteria, is administered to adult rats to induce diabetes by explicitly targeting and damaging the insulin-producing β cells in the pancreas." (PMID 39204115, 2024). "Patients with type 1 diabetes, gestational diabetes, or, in some cases, type 2 diabetes mellitus (T2DM) require insulin to control blood glucose." (PMID 38803476, 2024). "When the body is unable to make enough insulin or use it properly to control blood glucose levels, diabetes develops." (PMID 39238969, 2024). "Type of diabetes, duration of diabetes, current diabetes treatment (diet, medications, insulin), smoking history, alcohol consumption, known hypertension, any known diabetes complications, previous heart attack or stroke." (PMID 38272554, 2024). "This is why people with diabetes need to watch their diet, constantly monitor their blood glucose levels, remember to take insulin or other medicine, and engage in regular physical activity." (PMID 38667619, 2024). "Diabetes mellitus (DM) is a severe and chronic disease characterized by elevated blood glucose levels resulting from aberrant islet β-cell biology and insulin action." (PMID 38681772, 2024).
diabetes (continued). "Excess body fat results in reduced glucose tolerance and reduced insulin sensitivity, which in turn leads to insulin resistance and diabetes." (PMID 38667619, 2024). "For example, the right-shift of insulin dose-response curve is closely related to the development of obesity and diabetes; therefore, a mechanistic understanding of this right-shift would be beneficial to disease treatment." (PMID 39617270, 2024). "Among young people with T2D, 52% were prescribed insulin therapy, 85% metformin, and 10%–15% other diabetes medications." (PMID 40302977, 2024). "Compared to traditional diabetes treatments, cell therapy can restore endogenous insulin supplementation, but its large-scale clinical application is impeded by donor shortages, immune rejection, and unsuitable transplantation sites." (PMID 38966749, 2024). "GLUT4 is considered a key target for diabetes treatment since it is stimulated by insulin to transfer glucose from the outside of the cell and into muscle cells and adipocytes, thereby lowering the blood glucose level." (PMID 38611823, 2024). "Injection into lipodystrophied sites results in an abnormal absorption of insulin, leading to glycemic instability and uncontrolled diabetes." (PMID 39691127, 2024). "The observed increasing odds of diabetes with age concurs with findings from other studies, attributed to elevated glycated hemoglobin levels and changes in insulin sensitivity." (PMID 38941315, 2024). "Resistant starch is known for its the potential to improve glycemic control by modulating gut microbiota and enhancing insulin sensitivity, making it a promising candidate for diabetes management." (PMID 39835082, 2024). "Other diabetes biomarkers, such as HbA1c, GA, insulin, insulin antibodies, uric acid, lactate, and GADA, are discussed in detail." (PMID 39355278, 2024). "The mean diabetes duration and thepercentage of insulin users were 17.28 years (SD 9.75) and 62.26%, respectively, inthe in-person group." (PMID 38656030, 2024). "Diabetes mellitus (DM) is a prevalent metabolic disorder characterized by chronic hyperglycemia resulting from impaired insulin secretion, insulin resistance, or a combination of both." (PMID 38434702, 2024). "There can be many explanations for identified associations, including latent characteristics of those with the code (e.g., diabetes among those with a code for insulin), therefore characterizing the relation between codes can aid in interpretation." (PMID 38947037, 2024). "mTORC1 also contributes significantly to diabetes mellitus by regulating essential processes such as the insulin signaling pathway and insulin resistance." (PMID 39238386, 2024). "As diabetes progresses, many older adults require insulin therapy to effectively manage their blood glucose levels." (PMID 39074147, 2024). "For instance, the suppression of H19 has been shown to protect endothelial cells from high glucose-induced inflammation and oxidative stress by upregulating miR-29b, which plays a role in glucose balance and insulin secretion, impacting diabetes pathogenesis." (PMID 39765830, 2024). "After 30 min, the elevation of insulin in the P. copri treatment groups was significantly higher than that in the diabetes group." (PMID 38934548, 2024). "IGF-I is structurally and metabolically similar to insulin but the exact role in appetite regulation and contribution to obesity and diabetes is still poorly understood." (PMID 38612666, 2024). "Type 1 diabetes mellitus patients treated with either Deg‐100 or Gla‐300 as basal insulin were enrolled." (PMID 39588847, 2024). "CircGlis3 is related to lipotoxicity‐mediated β‐cell disease and diabetes through inhibiting cell growth and insulin production." (PMID 39239069, 2024).
diabetes (continued). "Of those with a diabetes diagnosis, 91.4% of women and 92.2% of men were on medication (insulin, tablets [e.g., Metformin or Amaryl], or both insulin and tablets), indicating generally good access to healthcare and medication once a diagnosis is received." (PMID 39033292, 2024). "The questionnaire was administered to 230 SNs focusing on their general knowledge of diabetes, insulin and glucagon, IP, diabetes complications, nutrition, physical activity, stress, comorbidities, and blood glucose measurements." (PMID 39195172, 2024). "These measurement increases were magnified in patients requiring insulin treatment for their diabetes." (PMID 39006603, 2024). "Insulin is essential for glycemic control, and the wide range of oral anti-diabetic medications used underscores the complexities of diabetes care." (PMID 39070354, 2024). "Diabetes has an insidious onset, with an imbalance between insulin secretion and insulin resistance, leading to a functional insulin deficit." (PMID 38611003, 2024). "As this category includes patients with both high insulin sensitivity and good beta cell function, they are likely to be in the initial stages of developing diabetes." (PMID 39217248, 2024). "It is found that pancreatic α cells can be transdifferentiated into insulin-secreting cells but the biological mechanism is unclear, limiting their further applications for diabetes treatment." (PMID 38966749, 2024). "In line with this, metformin plus insulin was more effective in lowering dimethylglyoxal in diabetes patients than was insulin." (PMID 38987239, 2024). "Once on insulin, they spoke of insufficient detail provided by professionals to help them actively manage their diabetes care:‘...So when I get my blood tests, I phone up and they will say they’re just normal." (PMID 38778253, 2024). "All Insulin products surveyed across the study area required 3 or more days’ wage for diabetes patients in both sectors." (PMID 38584277, 2024). "Islet transplantation is an effective method for treating uncontrollable diabetes, such as recurrent hypoglycemia and insulin desensitization." (PMID 39707176, 2024). "Insulin, a prototypical biological macromolecule, is an indispensable therapeutic agent for individuals diagnosed with type 1 and severe type 2 diabetes mellitus." (PMID 39065576, 2024). "Ob/ob mice develop insulin resistance due to leptin deficiency, become severe obese with moderate hyperglycemia and high insulin release capacity and are a model for metabolic syndrome/pre-diabetes." (PMID 39548491, 2024). "Information to support the self-management of diabetes in hospital is also available, as people with diabetes often have more knowledge of their own insulin and other specific requirements than the healthcare team managing them in hospital." (PMID 38953925, 2024). "This review highlights studies on diabetes management in older adults, assessing the impact of health education, diabetes management programs, treatments, mHealth, and advanced insulin delivery systems." (PMID 39765957, 2024). "Diabetes occurs when elevated blood sugar levels result from diminished pancreatic insulin production or reduced insulin sensitivity in tissues that ordinarily react to insulin signalling." (PMID 38786121, 2024). "Nowadays, insulin continues to be an agent of ordinary and necessary use in the pharmacological treatment of diabetes, firstly in T1DM and in gestational diabetes, where insulin is the only pharmacological option and the only considerable replacement therapy." (PMID 38672255, 2024). "TZDs have been used as antidiabetic drugs and act as insulin sensitizers in the treatment of type 2 diabetes mellitus." (PMID 38988496, 2024). "It was possible to successfully switch the therapy in patients with diabetes lasting more than 15 years and with duration of insulin therapy more than 6 years." (PMID 38792590, 2024).
diabetes (continued). "Growing research indicates that AD is essentially a metabolic disorder, exhibiting molecular and biochemical features similar to diabetes and other insulin-resistant conditions." (PMID 38659706, 2024). "In a diabetes stewardship program, pharmacists are actively involved in glycemic management, including daily BG assessment and insulin dose adjustment." (PMID 38919469, 2024). "Diabetes mellitus, a chronic metabolic disorder characterized by impaired insulin function or production, remains a significant global health concern." (PMID 38399334, 2024). "For instance, enhanced insulin sensitivity and glucose uptake by skeletal myocytes have been observed in exercising individuals with diabetes which clearly improved glycemic control in this cohort." (PMID 39633643, 2024). "Insulin aspart is a recombinant rapid-acting human insulin analogue utilised in the treatment of type-1 and type-2 diabetes mellitus." (PMID 38378730, 2024). "GLP-1R agonists are well-studied for the treatment of diabetes as they regulate blood glucose by increasing INS secretion and inhibit GCG secretion and appetite." (PMID 38313028, 2024). "As expected, pre-pregnancy HbA1c% and insulin requirements during pregnancy were significantly higher in women with pre-existing diabetes compared to those with GDM." (PMID 40071056, 2024). "Insulin resistance, a condition characterized by a weakened response to insulin in the cells, plays a crucial role in the development of metabolic syndrome and diabetes." (PMID 38791227, 2024). "On average both groups used 2.6 (SD 1.2 and 1.1) anti-diabetes medication classes and 73.6% and 74.9% of patients used insulin during the baseline period in the GLP1-RA and DPP4i groups, respectively." (PMID 39639039, 2024). "A1cs were lower than average in this sample, with 71% having an A1c <8%, and there were high rates of diabetes technology use with 83% using insulin pumps and 96% using continuous glucose monitors." (PMID 38774897, 2024). "We further showed that receptors for LIGHT on islet cells are upregulated and can induce beta cell death and impair insulin secretion from human pancreatic islets in vitro, thus contributing to occurrence of overt diabetes and its progression." (PMID 38685051, 2024). "The discovery of insulin represents one of the most valuable scientific events of the 20th century, as it significantly contributed to the comprehension of diabetes mellitus pathophysiology and had relevant fallouts from a therapeutic viewpoint." (PMID 39200316, 2024). "Insulin pump alarms alert people with diabetes when the insulin pump battery level is low, if the insulin reservoir levels are low, when insulin delivery is occluded, and several other events." (PMID 39738754, 2024). "After induction of diabetes in healthy mice, they were checked for fasting blood sugar level, serum insulin, serum creatinine, triglyceride, and HbA1c level." (PMID 38565861, 2024). "These advantages extend to improvements in insulin sensitivity and glucose uptake, enabling the optimization of type 2 diabetes mellitus management, with reductions in OAD requirements in some of those patients treated with baricitinib." (PMID 38541086, 2024). "Pre-diabetes and Type 2 diabetes mellitus (T2DM) accelerate memory loss, brain aging and increase risk for dementia via inflammation, impaired insulin-mediated brain signaling and oxidative stress." (PMID 39006824, 2024). "Increased aldosterone impairs insulin secretion and sensitivity, which is a key factor in the development of diabetes." (PMID 38678275, 2024). "Once diabetes was successfully established, the treatments were initiated with insulin subcutaneous injections (INS), 30 and 100 mg/kg oral doses of Vox2 (V30 and V100), and the combination of insulin with Vox2 (V30INS and V100INS)." (PMID 38675446, 2024). "Diabetes mellitus (DM) is a progressive and chronic metabolic disorder characterized by hyperglycemia due to impaired insulin levels, sensitivity, or action." (PMID 38970135, 2024).